IL6 (interleukin 6)
Diseases named in the same sentence as IL6 in open-access papers (continued):
Sharing a sentence is not in itself a finding about the gene and the disease.
Cirrhosis (continued). "One study that examined translocated microbial products and their ability to predict cirrhosis and progression to end-stage liver disease in HCV and HBV infection found elevated plasma levels of LPS, IFABP, IL-6, and sCD14 in patients with HCV or HBV compared to uninfected controls." (PMID 37626844, 2023). "Prior to the presence of cirrhosis, in ARLD and NAFLD, hepatic macrophages become activated by LPS, IFN-ɣ, and GM-CSF signalling and show pro-inflammatory cytokine/chemokine secretion (IL-6, IL-1β, and CCL2)." (PMID 36926073, 2022). "Functionally these activated macrophages were responsive to microbial challenges, which resulted in the production of pro-inflammatory cytokines (IL-23, IL-6, and TNF-α) and contribute to mucosal, epithelial, vascular and immunological barrier dysfunction in cirrhosis." (PMID 36926073, 2022). "Patients with alcoholic hepatitis and/or cirrhosis show elevated serum concentration levels of TNF-alpha and TNF-alpha-inducible cytokines/chemokines, such as IL-6, -8, and -18, and levels correlated with markers of the acute phase response, liver function, and clinical outcome." (PMID 35269779, 2022). "Higher risk scores were associated with increased disease severity, length of ICU stay and mortality: High NUTRIC and mNUTRIC revealed not only worse APACHE II and SOFA, but also more advanced stages of cirrhosis in terms of MELD and CHILD scores, higher IL6 as well as worse renal function." (PMID 32709104, 2020). "Detailed analyses of the distinct subsets revealed that TNF-α/IL-6 production in response to LPS was decreased in both CD14+HLA-DR+AXL+ monocytes and M-MDSCs when compared with CD14+HLA-DR+AXL− monocytes from patients with cirrhosis and HC." (PMID 31822557, 2020). "In order to confirm the risk factors of RFS in HCC patients, Cox proportional hazard analysis was performed with clinical factors (age, gender, maximum tumor size, MVI, cirrhosis, differentiation, HBsAg status, and AFP) and preoperative serum IL6, IL8, and TNF-α levels." (PMID 31781194, 2019). "High levels of interleukin-6 are related to adverse outcomes in the CVH, including greater severity, worse response to treatment and viral persistence, and evolution to cirrhosis, HCC, or death." (PMID 29033929, 2017). "IL-12, IL-6 and TNF-α levels were higher in alcoholic cirrhosis (p < 0.05 for all), while IL-1β and IL-10 levels were comparable between patients with alcoholic or HCV cirrhosis." (PMID 26343741, 2015). "Yet we observed presence or absence of cirrhosis in HCC patients not reflecting expression of IL-6, IL-27, TNF-α, and VEGF." (PMID 25908103, 2015). "Systemic inflammation is a major characteristic of cirrhosis and other chronic liver diseases with increased levels of pro-inflammatory cytokines and chemokines such as TNF-α and IL-6, which in turn can disrupt the integrity and function of the intestinal epithelial barrier." (PMID 25171482, 2014). "IL-6 is a multifunctional cytokine along with TNF-α activates hepatic stellate cells and increases the production of extracellular matrix proteins that finally leads to cirrhosis." (PMID 22013498, 2011). "The concentration of IL-6 was higher in patients with more advanced stage of carcinoma, as evidenced by the significantly greater difference in the concentration levels of this cytokine in patients in the BCLC B group compared to those in the BCLC A and cirrhosis (tumor-free) groups." (PMID 41379186, 2025). "Consistent with previous findings, we observed that the FSTL1 levels were elevated in the serum of cirrhosis patients and in carbon tetrachloride (CCl4)-induced model mice and were positively correlated with the serum TGF-β1, TNF-α and IL-6 levels in cirrhosis patients." (PMID 40050288, 2025). "Usually, PMs increase the IL-6 production following inflammatory exogenous stimuli such as LPS exposition; however, higher levels of IL-6 have been found in ascites patients with cirrhosis and no previous spontaneous bacterial peritonitis." (PMID 40149656, 2025).
Cirrhosis (continued). "In our study of hospitalized patients with cirrhosis, the AUC was 0.65 (95% confidence interval [CI]: 0.57–0.74, p = 0.002) for serum endocan, 0.69 (95% CI: 0.61–0.78, p < 0.001) for serum PCT, and 0.67 (95% CI: 0.59–0.76, p < 0.001) for IL-6 in the diagnosis of OF." (PMID 39724169, 2024). "Though levels of IL-6 and ammonia and alterations in the glutaminase gene have been reported as possible indicators of HE in patients with cirrhosis, they may not always be readily available within health care data sets." (PMID 37930150, 2023). "Patients with cirrhosis have lower levels of high-density lipoprotein (HDL) cholesterol and apolipoprotein A1, which further decrease upon decompensation, correlating with increased levels of TNF-α, IL-8, IL-6 and severe bacterial infection, and predicting patient mortality." (PMID 37822786, 2023). "In concordance with this published data, we detected in cirrhosis and HCC that with dysbiosis, a measurable shift occurs toward a systemic Th1/Th17 proinflammatory cytokine phenotype, characterised by increased levels of IFN- γ, TNF-α, IL-6 and IL-17 amongst others." (PMID 33858327, 2021). "In addition, circulating IL-6 in cirrhosis with PVT was further elevated compared to that in cirrhosis with non-PVT pigs, whereas nonsignificant alterations were identified as regards serum IL-8 and TNF-α levels." (PMID 32351989, 2020). "We also found that higher values of plasma biomarkers (IP-10, IL-8, IL-6, OPG, sVCAM-1, sICAM-1, and D-dimer) were related to higher values of liver disease severity (CTP), but only IP-10 and IL-6 had high accuracy in separating patients with Child-Pugh B cirrhosis (CTP 7–9)." (PMID 32587340, 2020). "Therefore, we aimed to elucidate the applicability of VCS parameters as potential predictors for infections in patients with cirrhosis and compare their reliability with traditional inflammatory biomarkers such as PCT, IL-6, and soluble hemoglobin clearance receptor (sCD163)." (PMID 31915467, 2019). "Moreover, significantly higher IL-6 concentrations were observed in the group with classes B and C liver cirrhosis, as compared to the group of alcoholics without cirrhosis." (PMID 26448742, 2015). "Using multivariate analysis, we determined that serum endocan was an independent predictor for OFs in cirrhosis, unlike PCT or IL-6." (PMID 39724169, 2024). "The suggested expression changes in HNF4A and IL6 mRNA, but not HNF1A were validated in liver tissue of patients with cirrhosis as compared to nine controls without." (PMID 36652164, 2023). "Compared with normal subjects, serum IGF-1 level is much lower and IL-6 levels were much higher in patients with cirrhosis, and there was a negative correlation between levels of IGF-1 and IL-6." (PMID 37881635, 2023). "A corresponding increase in IL-6 and the anti-inflammatory cytokine, IL-10 was induced by NAFLD-HCC BE compared to both NAFLD-cirrhosis and non-NAFLD control BE (P = 0.001 and P = 0.003, respectively)." (PMID 33420074, 2021). "Consistent with the observations in patients with cirrhosis ex vivo, AXL-expressing THP-1 cells produced less TNF-α and IL-6 in response to LPS when compared with non-transduced THP-1 cells." (PMID 31822557, 2020). "In the present study, the seroprevalence of HCMV and the IL-6 production were determined in patients hospitalized who were studied on the basis of HCC, cirrhosis and the presence or not of hepatotropic viruses." (PMID 22032643, 2011). "While LBP is increased in patients with ascites and hyperdynamic circulation and is of some prognostic significance in cirrhosis, in a recent study it was not significantly regulated across the stages of cirrhosis as compared to CRP, IL‐6, or procalcitonin in line with our findings." (PMID 40317887, 2025). "TNF-α and IL-6 production was reduced in cirrhosis compared with HC and incrementally decreased from Child A to C, and AD but remained preserved in patients with CLD without cirrhosis." (PMID 31822557, 2020).
liver disease (203 papers, 1997 to 2026). "As a key cytokine in the inflammatory cascade, IL-6 mediates hepatic immune activation and has been implicated in disease progression across liver disorders." (PMID 40969799, 2025). "For HSD17B13, patients with liver disease carrying the risk allele TT exhibited elevated levels of IL-6 in blood." (PMID 40995436, 2025). "In our study, CXCL9 and CXCL10 were associated with mortality and correlated with MELD scores, likely because they reflect the underlying severity of ALD and portal hypertension, whereas IL-6 and IL-8 mainly capture the superimposed acute inflammatory trigger." (PMID 41373861, 2025). "Proinflammatory cytokines, such as interleukin-6 (IL-6) and interleukin-8 (IL-8), are not only closely linked to inflammation but also play pivotal roles in liver disease and regeneration." (PMID 38233759, 2024). "During aging progression, the IL-6 level was gradually increased, which enhances its pro-inflammatory effects and even promotes the development of inflammation-associated liver diseases." (PMID 38890694, 2024). "Understanding the roles and underlying mechanisms of IL-6 in liver physiological and pathological processes is still an ongoing process, and is critical to the development of therapeutic strategies for liver diseases." (PMID 38890694, 2024). "These diets also influence inflammatory markers such as CRP, TNF-α, and IL-6, which are implicated in the development and progression of steatotic liver disease, contributing to hepatic inflammation and fibrosis." (PMID 39796579, 2024). "In a study examining microbial translocation in women co-infected with HCV/HIV, elevated levels of plasma sCD14, IFABP, and IL-6 were associated with the progression of liver disease." (PMID 37626844, 2023). "Among the well-recognized mediators, TNF-α, IL-6, and Il1β have been implicated in the regulation of inflammation in liver diseases." (PMID 36588728, 2022). "Multiple studies have reported an association of IL-6–174 G/C polymorphism with the pathogenesis of liver diseases including HCC derived from HCV." (PMID 36215278, 2022). "The findings are in contrast with a recent meta-analysis study that suggested a strong association between the gene polymorphism of IL-6 rs1800795 carrying the G allele and susceptibility to liver disease." (PMID 34572300, 2021). "Although IL‐6 is associated with many liver diseases and cancers, it is also crucial for liver regeneration." (PMID 31094067, 2019). "In our cohort, associations of elevated IL-6 & D-dimer scores with the risk of cancer, kidney and liver disease, and all-cause mortality individually were at least as strong as associations with CVD." (PMID 27171281, 2016). "Impaired hepatic function is associated with increased serum IL-6 concentrations in people with liver disease." (PMID 25658922, 2015). "When prevalent liver disease was excluded, serum IL-6 remained significantly associated with liver-related mortality in unadjusted (HR 2.28, 95% CI 1.27–4.10) and age-sex adjusted (HR 2.10, 95% CI 1.11–3.96) models only." (PMID 22514624, 2012). "In the present study in patients with ACLF, we observed elevated serum levels of five cytokines commonly associated with inflammatory liver disease (IL-6, IL-8, IL-10, TNF-α, and sTNF-αR1) at baseline." (PMID 17156425, 2006). "Moreover, the use of cytokines, such as IL‐6, to stimulate immune responses must be approached with caution, as elevated IL‐6 levels are associated with increased fibrosis in various liver diseases." (PMID 41487942, 2026). "In addition to IL-10, IL-6 has been implicated in the development of liver diseases and subsequent portal hypertension." (PMID 39997697, 2025). "This difference might be due to the specific pathology of the enrolled patients, elevated IL-6 being associated with a variety of liver diseases." (PMID 39596058, 2024).
liver disease (continued). "Results of animal studies mimicking liver diseases of various etiologies have suggested that targeting TNFα release with specific antibodies is associated with decreased expressions of several cytokines including IL6." (PMID 37683301, 2023). "Interleukin-6 (IL-6) is a pivotal cytokine in inflammation-associated liver disease, and the current evidence suggested it has both pro-inflammation and anti-inflammation effects where IL-6 released from adiposity can promote inflammation and muscle-derived IL-6 can ameliorate inflammation." (PMID 35747747, 2022). "Possible explanations for these findings, since they have also been shown in other studies, are related to the involvement of inflammatory cytokines in the early stage of many liver diseases, supporting the association of heavy alcohol intake and increased levels of IL-6 and CRP." (PMID 31071114, 2019). "Although our study cannot test this hypothesis, we believe that chronic exposure to excess IL-6 levels in the liver may cause persistent liver damage leading to progressive liver disease, further increasing the risk of HCC and liver-related mortality." (PMID 22514624, 2012). "Elevated IL-6 expression is associated with immune-mediated liver disease progression." (PMID 21394214, 2011). "Moreover, chronic inflammation and tissue injury, as observed in various gastrointestinal and hepatic disorders, maintain persistent IL-6/STAT3 activation that supports the proliferation of mutated epithelial cells and contributes to tumor initiation and progression." (PMID 41267807, 2025). "Additionally, other study findings showed that IL-6 polymorphisms rs1800795 and rs1800796 may be potential genetic factors in the development of liver diseases." (PMID 39997697, 2025). "Thus, IL-6 SNPs may be a possible risk factor to contribute to the susceptibility to liver diseases." (PMID 32266003, 2020). "Zn deficiency in patients with liver disease is caused by a variety of factors, namely, inadequate oral intake, diminished hepatic extraction, portosystemic shunts and the effects of cytokines (mainly IL-6) and endotoxins, and we assumed these conditions lead to poor nutritional status." (PMID 32857769, 2020). "An imbalance of cytokines, namely Interleukin-1β (IL-1β), IL-6, and IL-10, can lead to liver diseases, including fibrosis and acute inflammation." (PMID 40584441, 2025). "As reported by C. D’Melloand M.G. Swain (2011), cytokines TNF, IL-1β, and IL-6 arelikely to be key promoters of central neural alterations inchronic liver diseases." (PMID 40144377, 2025). "IL-6 has multiple context-specific functions, both promoting and inhibiting the progression of liver disease." (PMID 39908263, 2025). "The IL-17 signaling pathway indirectly triggers the release of proinflammatory cytokines, including TNF and IL-6, which subsequently activate the NF-κB pathway, thereby exacerbating inflammatory liver diseases and related pathological conditions." (PMID 40238193, 2025). "Consistent with our previous studies examining histological indicators of liver disease, IL-6 abundance also exhibited cumulative increases in the DualExp offspring." (PMID 39908263, 2025). "Although IL-6 is commonly viewed as pro-inflammatory, several studies indicate it can also play protective roles in metabolic and liver diseases." (PMID 41002415, 2025). "Therapeutically, these insights are relevant, as IL-6 and IL-11 signaling have emerged as promising targets for metabolic-inflammatory liver disease, with IL-11 shown to potentiate matrix deposition and hepatocyte dysfunction under metabolic stress." (PMID 41470883, 2025). "Current researches have demonstrated that TNF, IL-1α/β, IL-1Ra, IL-6, IL-18, IL-33, IL-36, IL38, CCL2 and CCR2 are closely associated with liver disorders." (PMID 41333471, 2025).
liver disease (continued). "The functional ID can be observed in inflammation accompanied by an increase in pro-inflammatory factors, like IL-6 and hepcidin, in liver disorders, and some genetic diseases (hemochromatosis)." (PMID 38762716, 2024). "Systemic inflammatory markers such as C-reactive protein (CRP), lipopolysaccharide (LPS), interleukin-6 (IL-6), tumor necrosis factor-alpha (TNF-α), soluble CD14 (sCD14), soluble CD163 (sCD163), and D-dimer are linked to cardiovascular and liver diseases." (PMID 39529759, 2024). "IL-6 signal, also considered as a double-edged sword, performs both pro-inflammatory and anti-proinflammatory roles in the pathogenesis of liver diseases." (PMID 38890694, 2024). "If repeated or chronic hepatic IL-6 inflammatory insults are raised, a set of liver diseases will be initiated." (PMID 38890694, 2024). "During the senescence of liver cells, including hepatocytes, cholangiocytes, and stellate cells, IL-6 is produced and participate in the development of liver diseases, especially cancer carcinogenesis and progression." (PMID 38890694, 2024). "The cytokines most commonly associated with hepatic disorders are the pro-inflammatory cytokines TNF-α, IL-1, IL-6, and transforming growth factor (TGF)-β." (PMID 38007457, 2023). "Similar results were also reported regarding the correlations of IL-6 levels with biochemical markers of liver disease reflecting its role in evaluating the degree of activity of the inflammatory process in the liver." (PMID 35119591, 2023). "Induction of inflammation has been implicated in IR-mediated hepatic disease, which was confirmed by the upregulated gene expression levels of Bax and IL-1β as well as upregulated protein expression levels of TNF-α and IL-6 in the vehicle-treated IR rats." (PMID 36655319, 2023). "Consistent with the broad anti-inflammatory effects of C15:0 shown in our current study, daily oral C15:0 supplementation over 12 weeks lowers the proinflammatory cytokines MCP-1, IL-6, and TNFα, as well as IgG, in animal models of metabolic and liver disease." (PMID 37960259, 2023). "In multivariate linear regression analysis, IL-6 was found to be statistically dependent on the degree of severity of liver disease (CP score) and on the severity of neoplastic disease, with a p-value of <0.001 and 0.044, respectively." (PMID 37173873, 2023). "Pro-inflammatory cytokines, such as tumor necrosis factor (TNF)-α and interleukin (IL)-6, play essential roles in the development of various inflammatory liver diseases that result in liver cirrhosis." (PMID 37895873, 2023). "TNF-α, IL-1β, IL-6, and IL-18 are often used as markers of inflammatory responses and are involved in the induction of liver diseases." (PMID 36865438, 2023). "On multivariate analysis, IL-6 levels were statistically dependent on the degree of liver disease severity (CP score) and HCC stages (p = 0.001 and p = 0.044, respectively)." (PMID 37173873, 2023). "Interleukin-6 (IL-6) plays a key role in the occurrence and development of liver diseases and the effects vary in different periods of disease progression." (PMID 35455983, 2022). "TNF-α and IL-6 are inflammatory mediators that contribute to the pathological complications observed in several hepatic diseases." (PMID 35877426, 2022). "Some studies showed that the liver disease of a patient was likely triggered by a host of proinflammatory cytokines, such as interleukin-1β (IL-1β), interleukin-6 (IL-6), and tumor necrosis factor (TNF-α), that contribute to hepatocellular damage." (PMID 35897657, 2022). "The inflammation observed in liver diseases including alcoholic hepatitis and acetaminophen overdose includes the activation of acute responses with IL-1 beta, IL-6, and TNF alpha." (PMID 35805080, 2022). "Alcohol can induce the increase of endotoxin level, activate Kupffer cells, and trigger the excessive production of TNF-α, IL-1β, and IL-6, which participate in the pathogenesis of liver diseases." (PMID 35409071, 2022).